CD4 (CD4 molecule)
Diseases named in the same sentence as CD4 in open-access papers (continued):
Sharing a sentence is not in itself a finding about the gene and the disease.
lymphopenia (continued). "However, in this previous study, help was provided by CD4+ T cells activated in vitro with antigen whereas, in the experiments reported here help was provided by memory-like CD4+ T cells generated in vivo upon lymphopenia induced proliferation." (PMID 20856822, 2010). "Interestingly, in our model, help could be provided by memory-like CD4+ T cells generated in vivo upon lymphopenia-induced proliferation." (PMID 20856822, 2010). "Several factors may be involved in this CD4+ T cell activation, including homeostatic responses to lymphopenia, increased availability of CD4+ T cell tropic and/or pro-inflammatory cytokines, reactivation of latent virus infections, and other potential changes in the lymphoid microenvironment(s)." (PMID 20126441, 2010). "However, the prolonged CD4 lymphopenia observed with fludarabine may be counterproductive from the depletion of helper CD4+ cells." (PMID 19270751, 2009). "It is possible that the phenotypic analysis of depleted lymphocyte subtypes at day 1 may improve the sensitivity of the day 1 model: in a recently reported study, patients with both day 1 CD4+ and CD56+ lymphopenia were found to be at high risk for FN in a series of 226 patients." (PMID 12610500, 2003). "Lymphocytes, including CD4+T, CD8+T, B cells, NK cells, and innate lymphoid cells (e.g. MAIT, γδ T), were markedly depleted in severe coinfection, indicating that lymphopenia is a prominent characteristic in severe coinfections." (PMID 41163794, 2025). "A typical pattern described is of CD4+ T-cell counts normalising through age through homeostatic proliferation, while CD8+ T-cell lymphopenia often persists into adulthood." (PMID 41230284, 2025). "Major hallmarks include: largely normal B cells, NK cell lymphocyosis, immature NK cells, T cell lymphopenia (increased CD4+, reduced CD8+), low TRECs, and predominantly memory and effector CD4+ T cells and Tregs." (PMID 40295428, 2025). "Lymphopenia is a frequent hematologic abnormality in SLE, affecting T lymphocytes—particularly CD4+ cells—more profoundly than B cells." (PMID 41157194, 2025). "Our results confirmed lymphopenia in COVID‐19 KTRs: CD3+ T cells, CD8+ T cells, CD4+ T cells, and B cells were decreased during infection." (PMID 41146434, 2025). "In cellular immunity we observed lymphopenia with decreased CD3+ T cells and CD4+ T helper cells in GAS-infected children." (PMID 39858946, 2025). "CD4+ T cells, γδ-TCR+ T cells and CD21+ B cells were impacted by lymphopenia, and initial immune activation was detected." (PMID 41510007, 2025). "In severe coinfected patients, we observed a depletion of lymphocyte cells, including B (except plasma cells), CD4+ T, CD8+ T, γδ T, MAIT, and NK cells, indicating that lymphopenia is a prominent characteristic in these patients." (PMID 41163794, 2025). "By the age of 18 years, routine laboratory testing revealed a marked decline in T-cell subsets: CD3+ at 27%, CD4+ at 59/μL, CD8+ at 19/μL, and absolute lymphopenia." (PMID 40901120, 2025). "The lymphocyte immunophenotyping of the APECED group showed an increase of CD3+, CD4 +, and CD8+ T cell lymphocytes and NK lymphopenia compared with the normal range." (PMID 38605470, 2025). "Decreased thymic activity and decreased numbers of naïve CD4+ and CD8+ T cells also correlate with lymphopenia." (PMID 40612959, 2025). "IL-7Rα expression was significantly downregulated in CD4+ and CD8+ naive and memory T cells from STING GOF mice (Fig. EV5A,C), indicating that T cell lymphopenia impacts T cell fate at early stage in the periphery of STING GOF mice." (PMID 40804163, 2025). "The most frequent immunological alterations were hypogammaglobulinemia (39%), low number of CD4 + cells (33%), low number of CD19 + cells (30%), lymphopenia (23%), serum IgE levels > 2000 UI/L (19%), neutropenia (11%), and low number of TH17 + cells (8%)." (PMID 38231401, 2024).
lymphopenia (continued). "CD3 lymphopenia was seen in 61 (52.6%) patients, CD4 and CD8 lymphopenia were present in 91 (78.4%) and 43 (37.1%) patients respectively, while inverted CD4/CD8 ratio was noted in 75 (64.7%) patients." (PMID 39072316, 2024). "Both IVIG monotherapy and IVIG plus methylprednisolone therapy can increase lymphocyte counts (e.g. CD4+T, CD8+T, and gdT cells) to address lymphopenia." (PMID 39524437, 2024). "In fact, regarding impaired cell-mediated immunity, patients with Good's syndrome occasionally present abnormal CD4+/CD8+ T lymphocyte ratio and CD4 T lymphopenia, which were normal in our case." (PMID 38836142, 2024). "Especially in LOF missense variants, patients additionally have abnormalities in their T-cell compartment with T-cell lymphopenia, elevated CD8+ T-cells and a decreased CD4/CD8 ratio." (PMID 38813543, 2024). "In the phase 3 trial in patients with WHIM syndrome, treatment with CXCR4 antagonist mavorixafor increased and corrected peripheral blood CD4+ and CD8+ T-cell lymphopenia." (PMID 39588369, 2024). "In summary, he was found to have a primary immunodeficiency displaying a CD4+ and CD8+ T cell lymphopenia within the broader context of a multisystemic disease." (PMID 39270020, 2024). "The total lymphocyte count (TLC) is classified as normal (≥1000 cells/mm3) or abnormal (<1000 cells/mm3), and grade 3/4 lymphopenia (<500 cells/mm3 for CD8+ T cells and <200 cells/mm3 for CD4+ T cells) is considered severe." (PMID 38390330, 2024). "Reduced thymic size was accompanied by decreased splenic CD4+ and CD8+ T cell numbers in CypKO animals, consistent with systemic lymphopenia." (PMID 39321290, 2024). "Because TH1 and TH17 contribute to pathogenesis of colitis driven by naïve CD4+ T lymphocytes, we sought to clarify the roles for cytokines IFN-γ and IL-17A in lymphopenia-induced immune responses of MP cells." (PMID 39630890, 2024). "Features within this signature included: CD4+ and CD8+ T cell lymphopenia, reduced frequencies of CD3+ T cells and myeloid dendritic cells (mDC), as well as diminished median HLA-DR expression within dendritic cells (DC), classical and intermediate monocytes." (PMID 38195661, 2024). "Persistence of the anti–PD-1 CAR T cells coincided with extended lymphopenia and accelerated SIV disease progression, the latter likely due to profound, persistent depletion of both the CD4+ and CD8+ memory T cell compartment." (PMID 38557496, 2024). "Since CD4+ TCR Vβ6+ cells contain a Tg-derived TCR, transient lymphopenia induced the rapid activation and differentiation of skin-reactive Th17 cells in Dsg3H1 mice in vivo." (PMID 38576231, 2024). "All patients had marked CD4 and CD8 T cell lymphopenia, which necessitated antibiotic prophylaxis with trimethoprim/sulfamethoxazole in 3 out of four patients." (PMID 39153074, 2024). "In our series, low CD4 T-cell count was seen in 31 (88.6%) patients, inverted CD4/CD8 ratio in 26 (74.3%) patients, and CD8 lymphopenia in 10 (28.6%) patients." (PMID 39072316, 2024). "Treatment with X4-185 normalized splenic T-cell abnormalities, correcting the reduced CD8+ T-cell numbers, restoring the CD4/CD8 T-cell ratio, and ameliorating peripheral blood T-cell lymphopenia." (PMID 39588369, 2024). "Apart from the elevation of inflammatory factors, cytokine storm was also manifested by severe CD4+ and CD8+ T cell lymphopenia and coagulopathy, which have been proposed as biomarkers for COVID severity." (PMID 38686388, 2024). "The findings indicate that the patient exhibited leukopenia, lymphopenia, and reduced numbers of CD3, CD4, CD16/56, and CD19 cells, indicating impaired T-cell development and compromised cellular immunity." (PMID 38350907, 2024). "Altogether, our results in Ripk1ΔCD4 mice show the essential role of RIPK1 scaffold function in the homeostasis of naive CD4+ and CD8+ T cells and FoxP3+ Treg cells and in preventing T cell lymphopenia." (PMID 38734851, 2024).
lymphopenia (continued). "Twenty-seven patients underwent a standard lymphocyte immunophenotyping, which showed generalized lymphopenia (low CD3+ cells), a decrease in CD4+ and an almost normal median CD8+ rate." (PMID 39328418, 2024). "SCI ECP and SCI LCP patients showed significant CD4+ and CD8+ T lymphopenia, ascribed to a reduction in naïve and CM subsets." (PMID 38139422, 2023). "Murine studies identify a correlation between surface expression of CD5, a marker of TCR signal strength on naive CD4+ and CD8+ T cells, and the intensity of lymphopenia-induced proliferation." (PMID 37856221, 2023). "The main abnormalities found were lymphopenia (absolute numbers/μL 932–1138 lymphocytes; normal values > 1500), with very low CD19+ B cells (2–15 cells/μL; normal values 65–700) and very low CD4+ T cell numbers (289–296/μL; normal values 500–1800)." (PMID 37371700, 2023). "In the lymphoid cell compartment of drug naïve patients with MS, we observed in RRMS during relapse a CD8+ T cell naïve lymphopenia and in TMS during relapse a CD4+ T cell lymphopenia." (PMID 36761741, 2023). "Extensive immunophenotyping revealed CD4 lymphopenia (455/mm3), CD8 lymphopenia (188/mm3), and CD16 + 56 lymphopenia (23/mm3)." (PMID 37235056, 2023). "Severe lymphopenia was observed in CDVC patients with the counts of total lymphocytes (0.9 × 109/L), CD4+ T cells (0.35 × 109/L), and CD8+ T cells (0.28 × 109/L) below their corresponding lower limits of normal range." (PMID 37773701, 2023). "Fourth, the potential anomalous tissue distribution of CD4 and CD8 T lymphocytes in chronic SCI patients can also be involved in the observed lymphopenia." (PMID 38139422, 2023). "CD4+ T cells skewed toward an inflammatory Th17 phenotype by exposure of IL‐6 and transforming growth factor (TGF)‐β,4, 5, 6 and lymphopenia which has been described as having a varying impact on total CD4+, CD8+ and B cell composition." (PMID 36353774, 2023). "Exhibiting a high level of CD8+ and CD4+ T cell activation, marked CD8+ T cell lymphopenia, and increased levels of CD8+ T cell senescence was associated with a higher mortality rate." (PMID 36675642, 2023). "CD3+ T cell lymphopenia and CD3+CD4+ T helper, and CD3+CD8+ T cytotoxic cell lymphopenia were not common, and all of them were observed in less than 15% of patients." (PMID 38813014, 2023). "CD4 and CD8 T lymphocyte subsets play an important role in SARS-CoV2 immune response and a marked lymphopenia characterized severe SARS-CoV2 infection." (PMID 35911743, 2022). "Among patients with isolated CD4 lymphopenia and variable serum immunoglobulin levels, 29 patients were found to have normal HLA-DR and DOCK8 expression whereas recent thymic emigrants (CD4+CD45RA+CD31+) were markedly reduced." (PMID 35655284, 2022). "The data showed a significant reduction in the levels of CD3+, CD4+, and CD8+ T cells and CD45+ cells in the moderate and under-medication groups, suggesting lymphopenia in those patients." (PMID 35196808, 2022). "Baseline immunological evaluation revealed neutropenia in 4/111 patients, lymphopenia in 20/112 patients, involving the CD3 + compartment in 22/92 patients, the CD4 + compartment in 15/92, the CD8 + compartment in 11/92, and the CD19 + compartment in 39/92." (PMID 35445287, 2022). "CD4+ and CD8+ T lymphopenia were defined as an absolute count of < 500/μL and < 224/μL respectively." (PMID 35546670, 2022). "A decrease in total lymphocytes (CD4 + and CD8 + T cells, B cells, and NK cells) has also been reported; however, the mechanism of lymphopenia is unclear and needs to be investigated further." (PMID 34463916, 2022). "Marked lymphocytopenia occurred in most patients during the acute phase of SARS and Middle East respiratory syndrome (MERS), with CD4+ and CD8+ T cells particularly affected." (PMID 35346253, 2022).
lymphopenia (continued). "In the present study, lymphopenia was also observed, due to the severity of the disease, although the number of CD3 T and CD4 T lymphocytes increased at the second and fourth months compared to baseline." (PMID 35313959, 2022). "Severity of lymphopenia on admission reflected in the depletion of all lymphocyte subsets, mostly CD3+, CD4+ and CD8+ cells." (PMID 35392095, 2022). "In this study, a significant decrease in lymphocyte subsets, including CD3+, CD4+, and CD8+ T cells, and NK cells, was observed in the PE group, indicating that lymphopenia was more notable in persistent virus-positive cases." (PMID 36620263, 2022). "Lymphopenia and suppressed T-cell activation; long-lived memory CD4+ and CD8+ T-cell responses—Polyfunctional CD4+ and CD8+ T cell responses." (PMID 35601440, 2022). "Compared to healthy controls (n=24), DLBCL patients (n=33) showed significant lymphopenia, due to low CD3+CD4+ T helper and CD3-CD56+ NK cell counts, while cytotoxic CD3+CD8+ T cell counts were similar." (PMID 36700229, 2022). "RTEs, Naïve and central memory CD4 cells, were also severely reduced in ESRD compared to controls, while CD4+CD28- cells were significantly increased, despite the general CD4 lymphopenia." (PMID 35615367, 2022). "After completion of rhATG induction therapy, T cells immediately started repopulating with faster repopulation of CD8+ T cells compared to CD4+ T cells leading to a CD4/CD8 inversion with prolonged and modest CD4 lymphopenia." (PMID 34526511, 2021). "In severe state of COVID-19 infection, the activated polyfunctional CD4+ and CD8+ T lymphocytes make the biggest defense against the coronavirus and decreasing their count results in lymphopenia in about 85% of patients with severe COVID-19 infection." (PMID 33962573, 2021). "The results showed significant progressive lymphopenia and depletion of lymphocyte subsets (CD3+, CD4+, CD8+ and CD19+) in correlation to the disease severity." (PMID 33937096, 2021). "We found that the rapid expansion of CD4+CCR5+ and CD8+ T cells during the first few weeks after HSPC transplantation is most likely due to lymphopenia-induced proliferation of residual endogenous cells after TBI rather than thymic reconstitution." (PMID 33432929, 2021). "SARS CoV-2 causes immune dysfunction or dysregulation leading to a decreased T-cell population which mostly affects the CD4+ CD8+ T-cell subset,induces lymphocytopenia, and eventually results in bacterial and fungal superinfection." (PMID 35747732, 2021). "Affected individuals had severe lymphopenia of NK cells and CD4+ T cells, reduced CD8+ T cells, agammaglobulinemia, abnormal distribution of progenitor cells in the bone marrow or B cell lymphopenia." (PMID 33477564, 2021). "The group 2 was characterized by increased total leucocytes counts, with a profound lymphopenia, a decreased proportion of CD8+ T cells and increased proportion of CD4+ T cells, a decrease in NK cells and an increase of neutrophils." (PMID 34322128, 2021). "In the present study, 92 (46.7%) patients showed significant neutrophilia and lymphopenia with pronounced reductions in peripheral blood CD3+, CD4+, and CD8+ cells." (PMID 33850192, 2021). "Total T cells (CD3+) as well as CD4+ and CD8+ T cells subsets were reduced in Opa1fl/fl;Lck-Cre+;mtYFPtg/+ mice, suggesting the development of lymphopenia." (PMID 33649469, 2021). "A transient lymphopenia affecting CD8+ and CD4+ T cells of all infected NHPs was observed from 3 to 10 DPI." (PMID 33398113, 2021). "Based on age- and gender-matched lymphocyte and lymphocyte subset references, 41 patients had total lymphopenia, 20 had CD3 lymphopenia, 15 had CD4 lymphopenia, 24 had CD8 lymphopenia, 19 had B lymphopenia, and 21 had NK lymphopenia." (PMID 33467982, 2021).
lymphopenia (continued). "The most common blood abnormalities in the entire cohort were lymphopenia (264/424 [62.3%]), and most patients had decreased T lymphocyte counts, including CD3 (214/319 [67.1%])`CD4 (204/319 [63.9%]) and CD8 (193/319 [60.5%])." (PMID 34551393, 2021). "Preexisting lymphopenia impairs the immune response to SARS-CoV-2, and current TB reduces the polyfunctional potential of SARS-CoV-2–specific CD4+ T cells." (PMID 33945513, 2021). "For example, increased levels of cytokines (IL-6, IL-10, and TNF-α), lymphopenia in T cells (CD4 + and CD8 +), and a decreased expression of IFN-γ in CD4 + T cells have all been reported." (PMID 33868085, 2021). "Lymphopenia is followed by repopulation of B cells, CD8+ T cells, and CD4+ T cells in sequence over time, with persistent depletion of CD4+ T cells for 3 to 4 years." (PMID 32539719, 2020). "In comparison with the nontreated patients, Tα1 significantly reduced the mortality rate of infected patients, and effectively restored T cell numbers in patients with severe lymphocytopenia (CD8+ T cells < 400/μL, CD4+ T cells < 650/μL)." (PMID 33584679, 2020). "The severe form of the disease is associated with increased cytokine levels (IL-6, IL-10, and TNFα), lymphopenia (in CD4+ and CD8+ T cells), and decreased IFNγ expression in CD4+ T cells." (PMID 32490731, 2020). "CD4 (“B” vs “D”: p = 0.03) and CD8 (“B” vs “D”: p = 0.02) T-cell AN were reduced at period B, being the “nadir” of lymphopenia, and then followed by a slow CD4 and CD8 T-cells increase (p<0.03)." (PMID 33178207, 2020). "Co-stimulation of CD4+ T cells by STING and TCR activation can induce growth arrest and lymphopenia by inhibiting mammalian target of rapamycin complex 1 (mTORC1) activation." (PMID 33335532, 2020). "Clinical features include extremely elevated cytokine levels (IL-6, IL-10, and TNF-α), lymphopenia (in CD4+ and CD8+ T cells), decreased IFN-γ expression in CD4+ T cells, and an increase in Th17 cell proportion." (PMID 32548750, 2020). "Most of the patients had elevated levels of C-reactive protein, and lymphocytopenia was common, especially in severe cases, which was thought to be a result of reduction of CD3+, CD4+ and CD8+ T cells." (PMID 32633729, 2020). "The recovery of T cells after the initial lymphopenia occurs over the following 2–3 weeks and is dominated by CD127-expressing effector and central memory CD4+ T cells, as well as CD57-expressing and differentiated memory CD8+ T cells." (PMID 32838342, 2020). "This lymphopenia is significantly observed on T cells (CD3+, both for CD4+ and CD8+ cells), on B cells (CD19+) and on NK cells (CD3–CD56+)." (PMID 33072114, 2020). "Previous study showed that lymphocytes and its subsets significantly decreased in SARS patients, while those with severe clinical illness or those who died had more remarkable CD4+ and CD8+ lymphopenia." (PMID 32275643, 2020). "In regard to the impact of lymphopenia, lymphopenic patients had increased Th2, CD38+CD4+ T cells, HLA-DR+CD4+ T cells, and Tregs." (PMID 33324414, 2020). "Absolute numbers of CD4 and CD8 T cells were reduced in most of KFD patients during the acute phase of illness, consistent with the lymphopenia noted on routine hematology." (PMID 32943687, 2020). "Lymphopenia in CKD/ESKD patients, especially naïve CD4+ and CD8+ T cells and T central memory, was previously attributed to decreased thymic output, increased apoptosis or shortening of telomere length." (PMID 33117396, 2020). "The MAIT cell lymphopenia was more profound than that observed for conventional CD8 and CD4 T cells and other unconventional T cell subsets." (PMID 32989174, 2020). "Immunophenotyping of lymphocytes disclosed an absolute CD4+, CD8+ and CD3+ T cells lymphopenia, with 0.066 ​× ​109/L, 0.134 ​× ​109/L and 0.180 ​× ​109/L, respectively." (PMID 34589827, 2020).